ALPL (alkaline phosphatase, biomineralization associated)
Diseases named in the same sentence as ALPL in open-access papers (continued):
Sharing a sentence is not in itself a finding about the gene and the disease.
prostate carcinoma (9 papers, 2017 to 2024). A carcinoma that arises from epithelial cells of the prostate gland. "Similar to ARCaPM, knockdown of ALPL expression in PC3 prostate cancer cells was also associated with a change in morphology." (PMID 28006818, 2017). "Knockdown of ALPL was also confirmed in PC3 prostate cancer cells, and associated with a reduction in cell viability and an increase in cell death." (PMID 28006818, 2017). "In contrast, high expression of ALPL in prostate cancer cells was associated with a significant reduction in disease-free survival." (PMID 28006818, 2017). "In this study, we have identified ALPL expression in metastatic prostate cancer cells, with high ALPL expression associated with a reduction in disease-free survival in patients with prostate cancer." (PMID 28006818, 2017). "Osteomimicry, which is defined as the phenotypic acquisition of bone forming properties by cancer cells, has been observed in prostate cancer cells in vitro, and the expression of osteoblastic factors such as ALPL by PC cells is associated with these phenotypic changes in vitro." (PMID 31136607, 2019). "In prostate cancer, ALPL was identified from the protein-protein interaction network, and the sub-networks revealed by this gene are involved in significant pathways." (PMID 34141614, 2021). "Reduced expression of tumor-derived ALPL inhibited mesenchymal-to-epithelial transition and the migration of advanced prostate cancer." (PMID 33858415, 2021). "Recent data supports a key role, however, of ALPL in prostate cancer cells themselves through the regulation of epithelial plasticity, invasion, and resistance to cell death." (PMID 31136607, 2019). "A significant increase in ALPL expression was detected in metastatic prostate cancer cells as compared with localised prostate cancer." (PMID 28006818, 2017). "To begin to determine the functional role of alkaline phosphatase in prostate cancer biology, we took molecular and pharmacological approaches to inhibit ALPL gene expression and alkaline phosphatase enzymatic activity." (PMID 28006818, 2017). "When gene expression data from patients with prostate cancer was stratified according to ALPL expression, Snail expression was significantly higher in ALPL-high samples, whereas E-cadherin expression was significantly lower." (PMID 28006818, 2017). "Alkaline phosphatase (ALPL), a homodimeric cell surface phosphohydrolase, is reported to play a controversial role in prostate cancer and ovarian cancer cell migration; however, the function of ALPL in LUAD and the related mechanisms remain unclear." (PMID 33858415, 2021). "Serum bone alkaline phosphatase (B-ALP, gene ALPL) has long been understood to be elevated in men with prostate cancer and bone metastases and was originally described by Huggins and Hodges to transiently rise and then fall after orchiectomy and clinical response to androgen deprivation therapy." (PMID 31136607, 2019). "To understand the genetic basis for the expression of B-ALP (ALPL gene) expression in CTCs and a broader osteomimicry phenotype in prostate cancer CTCs, we analyzed CTC DNA by array-based comparative genomic hybridization (aCGH) using previously established methods." (PMID 31136607, 2019). "In order to characterize ongoing bone cell activity in clinical cases of prostate cancer bone metastasis, we selected a set of genes to represent osteoclast activity (ACP5, CTSK, MMP9), osteoblast activity (ALPL, BGLAP, RUNX2) and osteocytes (SOST)." (PMID 29670000, 2018). "This is supported by a negative correlation between ALPL and E-cadherin gene expression in prostate cancer cells transduced with shALPL." (PMID 28006818, 2017).
Sepsis (9 papers, 2019 to 2025). Sepsis is defined as life-threatening organ dysfunction caused by a dysregulated host response to infection. "Prior time series analysis of septic patients identified three genes in the elastase family (ELANE, CTSG, PRTN3) and DEFA4 as candidate biomarkers for sepsis, while other studies likewise implicated NETosis genes including ALPL." (PMID 41385588, 2025). "In contrast to the ALPL group, all patients in the tHPE group had known additional diseases independent of HPP that are typical of tHPE, such as severe anemia, sepsis, and gastrointestinal, hematological, and rheumatological diseases." (PMID 39685776, 2024). "Likewise, ALPL and IL8RB/CXCR2 were quite variable in the more severe sepsis group with 3 additional patients showing abnormal scores with >25% change." (PMID 41385588, 2025).
Alzheimer disease (8 papers, 2014 to 2024). A progressive, neurodegenerative disease characterized by loss of function and death of nerve cells in several areas of the brain leading to loss of cognitive function such as memory and language. "While the physiological function of ALPLs are unknown, and no direct correlations have been made between ALPL variants and cognitive function, tissue non-specific ALPL is increased in Alzheimer’s disease patients." (PMID 25147783, 2014).
atherosclerosis (8 papers, 2017 to 2024). A disease characterized by the build-up of fatty material and calcium deposition in the arterial wall resulting in partial or complete occlusion of the arterial lumen. "Next, we analyzed the datasets (GSE43292, GSE12644, and GSE83453) obtained from aortas isolated from patients with atherosclerosis and stenosis for Cdon expression, together with aortic calcified markers such as Runx2, ALPL (alkaline phosphatase), and CD68." (PMID 36609601, 2023).
craniosynostosis (8 papers, 2013 to 2023). Craniosynostosis is defined as the premature fusion of one or more cranial sutures leading to secondary distortion of skull shape resulting in skull deformities with a variable presentation. "Multiple genetic variants of interest within ALPL have previously been identified, and are associated with occasional (<50%) occurrence of single-suture craniosynostosis." (PMID 36982425, 2023). "The ALPL gene, that encodes alkaline phosphatase, was significantly increased in metopic craniosynostosis in our primary and male-stratified models." (PMID 36982425, 2023).
osteogenesis imperfecta (8 papers, 2019 to 2026). Osteogenesis imperfecta (OI) comprises a heterogeneous group of genetic disorders characterized by increased bone fragility, low bone mass, and susceptibility to bone fractures with variable severity. "Allele A of ALPL (rs121918009) is associated with infantile and adult HPP, ALPL-related disorders, and osteogenesis imperfecta." (PMID 41158885, 2025). "Similarly, the expression of osteogenic signature genes was downregulated, including ALPL, an early marker of osteogenic differentiation, and COL1A1/2, two pathogenic genes for osteogenesis imperfecta." (PMID 37958322, 2023). "Alleles T, C, and A of ALPL rs121918007 are associated with adult HPP; meanwhile, allele A is also related to childhood, infantile, and odontohypophosphatasia presentations, serum alkaline phosphatase levels, choline phosphate levels, osteogenesis imperfecta, and inborn genetic diseases." (PMID 41158885, 2025).
kidney stones (7 papers, 2015 to 2025). "Four out of five patients with a mutation of c.1559del in ALPL had nephrocalcinosis and/or kidney stones." (PMID 39926094, 2025). "Four out of five patients with a heterozygous variant of c.1559del in ALPL had nephrocalcinosis and kidney stones." (PMID 39926094, 2025). "As alkaline phosphatase (ALP) hydrolyzes pyrophosphate into free phosphate, the risk of nephrolithiasis associated with the variants of ALPL should be dependent on the balance between stone-inhibiting pyrophosphate and phosphate in the kidneys." (PMID 35741705, 2022). "In this study, we showed that the TT genotype of rs1256328 in ALPL associated with higher susceptibility of nephrolithiasis in a Taiwanese population, which is consistent with a previous study in Icelandic population." (PMID 31754202, 2019). "Results revealed that subjects with minor TT genotype at rs1256328 (alkaline phosphatase, liver/bone/kidney (ALPL)) have higher susceptibility to nephrolithiasis (odds ratio (OR) = 2.03, p = 0.0013)." (PMID 31754202, 2019). "We screened the kidney stones associated variants for their association to serum level of biochemical traits and detected association of variants at ALPL with ALP, SLC34A1 with PTH, and creatinine, phosphate and CLDN14 with PTH, magnesium and potassium." (PMID 26272126, 2015). "We identify sequence variants associating with kidney stones at ALPL (rs1256328[T], odds ratio (OR)=1.21, P=5.8 × 10−10) and a suggestive association at CASR (rs7627468[A], OR=1.16, P=2.0 × 10−8)." (PMID 26272126, 2015). "We observe a genome-wide significant signal with two fully correlated markers associating with kidney stones in ALPL at 1p36.12, represented by rs1256328 [T] (minor allele frequency (MAF)=17.79%, OR=1.21, P=5.8 × 10−10)." (PMID 26272126, 2015). "Moreover, two studies each were identified that evaluated associations of the alkaline phosphatase, liver/bone/kidney (ALPL) gene (rs1256328) and matrix Gla protein gene (rs4236) polymorphisms with recurrent kidney stones." (PMID 33956883, 2021). "In summary, this study successfully replicated an association of SNPs in ALPL and RGS14, rs1256328 and rs12654812, with susceptibility to nephrolithiasis in a Taiwanese population." (PMID 31754202, 2019). "Since GTEx portal only collects limited cell types, and much evidence has suggested an important role of ALPL in the pathophysiology of nephrolithiasis via phosphate regulatory pathways." (PMID 31754202, 2019). "It’s very likely that dysfunction of either ALPL or RGS14 influence the homeostasis of calcium and phosphate that increase the risk to nephrolithiasis." (PMID 31754202, 2019). "A missense variant in ALPL (rs34605986 [A], MAF=15.21%, NP_000469.3:p.Val522Ala) that correlates with rs1256328 (r2=0.73) also associates with kidney stones (OR=1.19, P=8.9 × 10−8)." (PMID 26272126, 2015). "In summary, we report three uncorrelated (r2<0.0062 for all pairs) genome-wide significant signals at the ALPL locus associating with ALP and kidney stones (rs1256328 ), ALP and serum phosphate (rs12132412 and rs1976403) and ALP (rs149344982)." (PMID 26272126, 2015). "Our results, for variants in ALPL that either increase or decrease ALP levels, suggest that the effect of ALPL on extracellular pyrophosphate metabolism can influence kidney stone formation." (PMID 26272126, 2015). "Interestingly, rs12132412 and rs1976403 have little correlation with rs1256328 and ALPL p.Arg152His that show association with kidney stones and demonstrate significant associasion with ALP at the ALPL locus (r2<0.0062)." (PMID 26272126, 2015). "Therefore, further studies are needed to investigate whether rs1256328 (ALPL) and rs12654812 (RGS14) have synergic effects in the susceptibility of nephrolithiasis." (PMID 31754202, 2019).
kidney stones (continued). "Within ALPL, we also detect a low-frequency missense variant (rs149344982[A], MAF=1.42%, NP_000469.3:p.Arg152His), which associates strongly with reduced serum ALP levels (effect=−45.9 s.d.%, P=9.84 × 10−105) and suggestively with reduced risk of kidney stones (OR=0.742, P=8.1 × 10−3)." (PMID 26272126, 2015). "The observation of three uncorrelated signals at ALPL associating with ALP levels which do not predict their associations with serum phosphate and kidney stones is noteworthy." (PMID 26272126, 2015).
hypophosphatemia (6 papers, 2014 to 2025). Lower than normal levels of phosphates in the circulating blood. "The ALPL (Alkaline Phosphatase, Biomineralization Associated) mutations cause hypophosphatemia, mainly characterized by defects in bone and tooth mineralization." (PMID 39299017, 2024). "Hypophosphatemia (HPP) is an uncommon metabolic disorder caused by hereditary loss-of-function mutations in the ALPL gene." (PMID 36653784, 2023). "Studies have also shown that ALPL is associated with hypophosphatemia, skeletal development, cardiovascular disease, and acute kidney injury." (PMID 33858415, 2021). "Studies of the gene encoding alkaline phosphatase (ALPL) are focused mainly on hypophosphatemia." (PMID 33858415, 2021). "HPP is an inborn error of metabolism characterised biochemically by low serum alkaline phosphatase (ALP) activity (hypophosphatemia) and caused by a loss-of-function mutation within the gene encoding tissue-nonspecific alkaline phosphatase (TNAP) (ALPL; OMIM#171760) on chromosome 1p36." (PMID 24906390, 2014).
osteoarthritis (6 papers, 2010 to 2022). A noninflammatory degenerative joint disease occurring chiefly in older persons, characterized by degeneration of the articular cartilage, hypertrophy of bone at the margins and changes in the synovial membrane. "The most common rheumatologic diagnoses in ALPL-positive patients were osteoarthritis, rheumatoid arthritis, spondyloarthritis, and collagenosis." (PMID 36514157, 2022).
meningioma (5 papers, 2015 to 2024). A generally slow growing tumor attached to the dura mater. "One of the few prognostic indicators for human meningiomas is the loss of 1p (monosomy 1p) which correlates with a loss of expression of ALPL." (PMID 29073243, 2017). "The molecular pathway alterations caused by the reduced ALPL in meningioma is still needed to be investigated further though a few studies uncover the association of ALPL and NOTCH1 regulation in human epithelial cells and ALPL is one of the key hub genes in glioblastoma." (PMID 33807688, 2021). "ALPL is identified as the top featured gene of all subtype 3 DEGs contributing to the features in subtype 3 of meningioma." (PMID 33807688, 2021). "Thirdly, the prediction capacity of ALPL for meningioma recurrence needs to be validated externally." (PMID 33807688, 2021). "Further, our results of random-forest-based machine learning identified Alkaline Phosphatase (ALPL) is the feature gene in the most aggressive subtype of meningioma." (PMID 33807688, 2021). "Our findings identified low expression of Alkaline Phosphatase (ALPL) is the most significant feature in progressive subtype of meningioma." (PMID 33807688, 2021). "Therefore, prior to the clinical application, the assay designed for ALPL also should be elaborately tested for clinical utility in a large perspective cohort where meningioma patients developing to recurrence are recruited." (PMID 33807688, 2021). "Conversely, ALPL functions as a tumor suppressor gene in meningioma and ovarian cancer." (PMID 33858415, 2021). "To further explore whether ALPL could be used for the predictive biomarker of meningioma progression, we performed the prediction capacity analysis by the receiver operation curve (ROC)." (PMID 33807688, 2021). "ALPL has been previously recognized as a candidate tumor suppressor gene in meningiomas." (PMID 29073243, 2017). "In our study, ALPL was 4.7 fold underexpressed in meningiomas compared to control meninges." (PMID 29073243, 2017). "Although RF predicts TIMP3, INMT and SLC16A1 followed by ALPL as the important feature genes in subtype 3, the expressions of these three genes are not consistently lower or higher than all other subtypes of meningioma, which restricts their potent of being biomarkers for meningioma." (PMID 33807688, 2021).
cholestasis (4 papers, 2020 to 2024). Impairment of the bile flow caused by obstruction within the liver, or outside the liver in the bile duct system. "High levels of ALPL have been associated with an increased risk of liver fibrosis and bile duct obstruction, but further research is needed to draw more definitive conclusions." (PMID 39408831, 2024). "ALPL is commonly used to evaluate acute liver damage and cholestasis." (PMID 33858415, 2021).
chronic kidney disease (4 papers, 2019 to 2023). Impairment of the renal function secondary to chronic kidney damage persisting for three or more months. "Similarly, an ALPL inhibitor was found to be a potential treatment for cardiovascular disease by attenuating arterial calcification in a non-chronic kidney disease context." (PMID 34490374, 2021).
hepatocellular carcinoma (4 papers, 2018 to 2025). A malignant tumor that arises from hepatocytes. "A previous study has shown that immunosuppressive neutrophils expressing CD10 and ALPL contribute to the resistance of anti-PD-1 therapy in hepatocellular carcinoma by facilitating the development of irreversible TEX." (PMID 40226355, 2025). "NR1I2, ESR1, ALPL, MME, IGF1, NR3C2 and PTGS2 were differentially low expressed in hepatocellular carcinoma tissues." (PMID 38842135, 2024).
odontohypophosphatasia (4 papers, 2022 to 2025). A particular form of hypophosphatasia (HPP) characterized by reduced activity of unfractionated serum alkaline phosphatase, premature exfoliation of primary and/or permanent teeth and/or severe dental caries, in the absence of skeletal system abnormalities. "It is not clear whether this ALPL loss-of-function variant is in keeping with HPP or odontohypophosphatasia, or the degree to which it may ameliorate the ENPP1 phenotype." (PMID 41445557, 2025).
chondrocalcinosis (3 papers, 2019 to 2022). An acute episode of pain, swelling, and redness, sometimes associated with fever. "Five out of 7 patients showing a positive genetic test (i.e., a mutation in the ALPL gene) presented with a history of fractures, one of them presented with chondrocalcinosis, and two of them reported dental abnormalities." (PMID 31267001, 2019). "Chondrocalcinosis (OR 29.12; 95% CI 2.02–1593.52) and dental disease (OR 8.33; 95% CI 0.93–143.40) were associated with ALPL mutation, independent of BMI." (PMID 36514157, 2022).
COVID-19 (3 papers, 2021 to 2025). A disease caused by infection with severe acute respiratory syndrome coronavirus 2. "Another study has measured RNA markers in patients with varying degrees of disease and found that ALPL RNA concentrations were significantly higher in severe cases of COVID-19 than in episodic/moderate cases." (PMID 40566633, 2025). "This conjecture is also consistent with the conclusion that ALPL serves as a biomarker for severe COVID-19." (PMID 40566633, 2025). "A study demonstrated that ALPL was associated with disease severity and pulmonary fibrosis (a major complication of COVID-19) in COVID-19, and by neural network modeling analysis, ALPL may be a potential biomarker for identifying the severity of COVID-19." (PMID 40566633, 2025). "A strong relationship between ALPL and COVID-19 has been revealed in other studies." (PMID 40566633, 2025). "In addition, novel COVID-19 drugs are being developed that target ALPL as a therapeutic target for the disease." (PMID 40566633, 2025). "We found 35 novel drugs that inhibit targets (ALPL, CXCL8, and IL6) already in clinical trials for COVID-19." (PMID 34582497, 2021). "As per univariate and multivariate prognostic analyses, a few important genes, including ALPL, ANGPT2, CD4, G6PD, SERPINE1 and TNNI3, may serve as independent prognostic factors for HCC patients with COVID-19." (PMID 36275701, 2022). "We also identified 35 drugs targeting ALPL, CXCL8, and IL6 that were not previously tested against COVID-19 symptoms and could be repurposed for anti-SARS-CoV-2 management." (PMID 34582497, 2021).
diabetes (3 papers, 2021 to 2022). "Reduced levels of ALPL are observed not only in children with diabetes, but also in adults with diabetes-induced osteopenia." (PMID 33923498, 2021).
fibrosis (3 papers, 2020 to 2025). the formation of excess fibrous connective tissue in an organ or tissue in a reparative or reactive process.